BMI1 (BMI1 proto-oncogene, polycomb ring finger)
Diseases named in the same sentence as BMI1 in open-access papers (continued):
Sharing a sentence is not in itself a finding about the gene and the disease.
tumor (continued). "On the one hand, TiBcs have the function of promoting tumors by producing IL-10, TGF-β, and IL-35; by the lymphotoxin/ IKKa-BMI1 signaling pathway; or by directly promoting tumor progression through engaging PD-L1/PD-1 molecules." (PMID 33465122, 2021). "Western blotting analyses of tumor tissue lysates showed that Cisplatin induced Bmi-1 expression in UM-SCC-22B-naive tumors." (PMID 34689150, 2021). "Multiple studies have demonstrated a tumor-promoting function of BMI1, a ubiquitin ligase and PRC1 component, in DIPG." (PMID 34277419, 2021). "Results of the Western blot analysis also showed increased expression of Bmi1 and Sox2, which are markers for tumor-initiating cells, in the drug resistant cells." (PMID 34681918, 2021). "Previously, high BMI1 expression, which contributes to tumor cell growth and chemotherapy resistance, was described for D17 cells." (PMID 34201296, 2021). "Mice bearing MM with wt MΦs had more MM-MΦs in tumor beds relative to those bearing MM with BMI1-KO MΦs, implying higher proliferation of wt MM-MΦs in vivo." (PMID 33993198, 2021). "We chose two IDH-wild-type GBM cell lines (U87MG and LN428) and two GIC lines (U3118 and U3082) with levels of BMI1 overexpression mirroring the variation observed in GBM tumour samples." (PMID 34316702, 2021). "Surprisingly, lineage tracing of emergent tumours in this model showed that they harbour a reduced number of Lgr5+ cells but an increased proportion of Bmi1+ cells." (PMID 33673710, 2021). "The correlation of LSD1 and Bmi-1 was further validated by examining the expression of these two molecules in 85 primary HNSCC tumor samples using immunohistochemical staining." (PMID 34689153, 2021). "The BMI1 expression in the tumor tissues of BCa patients was negatively correlated with miR-381 expression." (PMID 33407350, 2021). "In conclusion, this study revealed that abridged miR-135a expression in OS, while restoration of miR-135a suppressed tumor invasion and pulmonary metastasis by targeting BMI1 and KLF4 in vitro and in vivo." (PMID 33828977, 2021). "By contrast, the NK-exosome-treated tumor group exhibited a significant reduction in Bmi-1, MMP-3, IL-1β, IL-6, TNF-α, Bax, Bcl-xL, and PCNA expression compared with that in the tumor group." (PMID 34527741, 2021). "By inhibiting BMI1 using a small molecule inhibitor and combining this with obatoclax, the authors showed significant improvement in survival and tumour regression." (PMID 34137158, 2021). "Bmi-1 is the direct target of miR-15a, miR-128, miR-192 and miR-194, the tumor suppressor miRs that are up-regulated in human gastric carcinoma cells and tissue samples treated with metformin." (PMID 33849540, 2021). "Overexpression of BMI1 partially blocked the tumor suppressing roles of miR-381 in cell malignancy and tumor growth (all p < 0.05)." (PMID 33407350, 2021). "In patients, higher levels of EZH2 and BMI1 expression correlate with poorer tumor differentiation/higher grade and worse survival." (PMID 34968245, 2021). "As for in vivo, we found cells transfected with BMI1-OE led to significantly increased tumor growth rate and weight in nude mice (n = 8)." (PMID 33407350, 2021). "We show that BMI1 inhibits the tumor suppressive Hippo pathway and, conversely, that BMI1 disruption upregulates Hippo signaling." (PMID 33523558, 2021). "In the MM tumor microenvironment, hedgehog signaling in MΦs was activated by MM-derived sonic hedgehog, and BMI1 transcription subsequently activated by c-Myc." (PMID 33993198, 2021). "By generating the heat map, two groups were identified: Group 1 contained tumour samples with high expression of BMI-1/CD44, and low expression of ALDH1/Nanog/SOX2, which correlated significantly with a higher grading (G1 vs. G2/3; p = 0.029)." (PMID 33009929, 2021).
tumor (continued). "Our current model summarizes these data, which suggest that BMI1 promotes tumor cell growth by inhibiting LATS1/2 phosphorylation and allowing YAP/TAZ/TEAD to transcribe canonical target genes (such as AXL, CYR61, and CTGF)." (PMID 33523558, 2021). "Bmi-1 is another TF that has been found to importantly regulate the self-renewal capacity of both normal and tumor stem cells." (PMID 33639931, 2021). "In the TCGA database, BMI1 expression was elevated in primary tumor tissues compared to normal tissues (p < 0.001)." (PMID 34442383, 2021). "We show that BMI1 interacts with members of the spliceosome machinery, a regulatory mechanism characterized by extensive and dynamic protein interactions during tumour formation." (PMID 34316702, 2021). "Then, it was found that BMI1 expression was increased in tumor tissues as compared to the adjacent tissues, and similarly, the BMI1 expression was also higher in BCa cell lines than that in bladder epithelial cells." (PMID 33407350, 2021). "Bmi1+ cancer cells can form tumour clones with comparable architectural and molecular features seen in primary tumours." (PMID 34680271, 2021). "Both EZH2 and BMI1 have also been implicated in pancreatic cancer stem cell maintenance, a functional subset of tumor cells thought to promote PDA chemoresistance and tumor relapse." (PMID 34968245, 2021). "Of note, a high portion of BMI1‐expressing cells were confined to undifferentiated tumors and tumors with invasion to optic nerve and/or choroid, implying a role for BMI1 in RB progression to advanced tumor stages." (PMID 32840881, 2021). "Western blottings of representative PDX tumor lysates showed that Tocilizumab inhibited Bmi-1 expression in vivo, even in the presence of Cisplatin." (PMID 34689150, 2021). "Tumor volume and circulating monoclonal protein measurement revealed significantly faster tumor growth in mice bearing MM with wt MM-MΦs relative to mice bearing MM with BMI1-KO MM-MΦs." (PMID 33993198, 2021). "Consistently, the level of BMI1 in tumor tissues from patients resistant to GC chemotherapy was significantly higher than that sensitive to GC chemotherapy." (PMID 34270461, 2021). "Gain-of-functions of miR-381 and BMI1 were performed to identify their functions on BCa cell behaviors as well as tumor growth in vivo." (PMID 33407350, 2021). "miR-128, targets B-lymphoma Mo-MLV insertion region 1 (BMI1) which promotes cell proliferation and tumor growth and binds to the promoter region of PTEN thereby suppressing its expression." (PMID 34484116, 2021). "Among all tumor samples, the overall accordance rates, which combine the results of Gli1-negative and Gli1-positive samples, between Gli1 and BMI1 or SOX2 expression were 85% and 84%, respectively." (PMID 33499351, 2021). "Nevertheless, the BMI-1 expression was correlated with clinicopathological data that offer a solid functional image of the tumor progression." (PMID 34199929, 2021). "Preclinical studies demonstrate that inhibition of BMI1 impaired tumor cell proliferation, promoted cell differentiation, and sensitized cells to radiation induced DNA damage." (PMID 34277419, 2021). "B-lymphoma moloney murine leukemia virus insertion region-1 (Bmi-1) as an oncogene, is involved in self-renewal and differentiation of stem cells, tumor genesis and metastasis." (PMID 33849540, 2021). "H3K4Ac marks are also present in the transcription regulators Forkhead Box F1 (FOXF1) and BMI1 Proto-Oncogene, Polycomb Ring Finger (BMI1), that promote tumor progression and stemness." (PMID 33803458, 2021). "It was observed that AL has a significant effect on BMI1 inhibition, and BMI1 positively promotes the proliferation and metastasis of tumor cells." (PMID 33927214, 2021). "A study explored CSC-3436, a flavonoid derivative, to inhibit TWIST-induced EMT, metastases, and tumor-initiated ability through the TWIST/BMI1-Akt/β-catenin pathway." (PMID 35048023, 2021).
tumor (continued). "Reducing expression of BMI1 promotes apoptosis and/or aging of tumor cells, while enhancing sensitivity of tumor cells to chemoradiotherapy." (PMID 33927214, 2021). "In lung cancer, H3K4Ac marks have been detected in the transcription regulators FOXF1, and Bmi1 that promote tumor progression and stemness." (PMID 33803458, 2021). "A reduced tumor burden along with decreased expressions of the BMI1 oncogene, the EMT markers as well as the cisplatin transporter ATP7B were reported in treated mice as compared to negative controls." (PMID 34072348, 2021). "Emergent tumours in this model display activation of β-catenin signalling and elevated expression of the BMI1 stem cell marker, consistent with the notion that the AvrA effector subverts host ISC-signalling pathways." (PMID 33673710, 2021). "Recently, it has been demonstrated that combination therapy with PTC-209 augmented PD1 immune checkpoint blockade and eliminated BMI1+ CSCs by inducing tumor cell-intrinsic immunity, resulting in the inhibition of metastasis and relapse of HNSCC in vivo." (PMID 35048028, 2021). "BMI1+ CSCs have increased AP-1 activity and are cisplatin-resistant, and combination therapy that targets BMI1+ CSCs and the tumor bulk yields better outcomes and effectively prevents metastasis." (PMID 35048023, 2021). "Monotherapy alone against ESCC tumor growth near the limits of detection and combinational therapy of Bmi1 inhibitor and cisplatin were the most effective in reducing tumor burdens." (PMID 32884573, 2020). "Although BMI1 showed only moderate expression changes in tumor as compared to normal cells (approximately 20% higher; from 42.90 to 51.19), its co-binding relationship with other factors changed dramatically." (PMID 32615918, 2020). "In the luminal oestrogen receptor-positive (ER+) BC, BMI1 showed significantly higher expression compared to ER− tumours." (PMID 32524353, 2020). "We found that targeting both the tumor bulk and Bmi1+ cells achieved the most efficacious tumor control." (PMID 32884573, 2020). "Conclusively, our results show that DEX treatment elevated ROR1 expression, which in turn enhanced RhoA, YAP/TAZ, and BMI-1 levels in OC tumor cells and is indicative of a DEX-mediated stemness phenotype via ROR1 signaling." (PMID 32989221, 2020). "This shows that in ESCC, the offspring cells differentiated from Bmi1+ cells located in the basement membrane gradually develop into tumor parenchyma cells of ESCC over time." (PMID 32884573, 2020). "Other factors including FOXF1 and Bmi1 are also transcription regulators that promote tumor progression and tumor stemness." (PMID 32114978, 2020). "The comparison between normal and tumor tissue revealed frequent overexpression of SOX9 and BMI1, whereas p21CIP levels were similar or decreased in tumor samples." (PMID 31941916, 2020). "This was regulated by the hedgehog pathway (Gli2, Bmi1, and Sox 2) to promote tumour initiation and maintenance." (PMID 32316619, 2020). "Analyses of MB tumor samples from patients reveals expression of the stemness markers BMI1 and CD133 in all MB molecular subgroups, and NaB is able to reduce BMI1 and CD133 expression in cultured MB cells." (PMID 32754588, 2020). "Treatment with a related but more specific BMI1 inhibitor resulted in tumor regression and maintenance of cell identity." (PMID 31934644, 2020). "Subsequently, we found that ablation of Bmi1+ cells from mice with ESCC led to inhibition of tumor growth." (PMID 32884573, 2020). "Overall, these results show that the ectopic restoration of BMI1 in SOX9-silenced cells recovers the aggressive phenotype of tumor cells." (PMID 31941916, 2020). "Of the TCGA datasets, we found that the dataset with the highest number of tumour samples (hthgu133a, n = 548) showed a strong and significant inverse correlation between BMI1 and EFNA5, whilst the other three datasets did not (data not shown)." (PMID 31988455, 2020).
tumor (continued). "Similar results were found by Western blotting, which showed that knockdown of CBX4 suppressed the expression of BMI‐1 in tumour tissues." (PMID 31724308, 2020). "We utilized genetic lineage tracing analysis and identified a subpopulation of Bmi1+ tumor cells that give rise to progressively growing epithelial clones." (PMID 32884573, 2020). "Our study focuses on the oncogene BMI1 because it plays an important role in the development of tumor metastasis, stemness maintenance, and chemo- and radiotherapy resistance." (PMID 32726929, 2020). "In recent years, the role of Bmi-1 in tumor cell escape from apoptotic cell death and in the failure of chemotherapy has been identified." (PMID 32059385, 2020). "We also found that the repression of EfnA5 by Bmi1 contributes to tumour growth in vitro and in vivo in our mouse model." (PMID 31988455, 2020). "Bmi-1 was proven to induce the expression of miR-27a and miR-155 and thus promote tumor metastasis and chemoresistance by targeting RKIP in GC." (PMID 32580736, 2020). "The effects of the Bmi-1/miR-27a/RKIP and Bmi-1/miR-155/RKIP axes on tumor growth, proliferation, migration, invasion, colony-formation ability, metastasis and chemoresistance were investigated both in vitro and in vivo." (PMID 32580736, 2020). "Bmi‐1 inhibits the expression of tumour‐suppressor genes, including p16, p19 and p27, to maintain the self‐renewal of bone marrow mesenchymal stem cells." (PMID 32583517, 2020). "In contrast, in the one animal treated with A1016 and that still presented a small tumor of 0.6 mm in diameter, the tumor remained BMI1 and SOX2 positive, although EZH2 levels were reduced." (PMID 31934644, 2020). "First, we noted that ectopic expression of BMI1 increased the number of tumor cells or restored the number counted in SOX9-silenced cultures." (PMID 31941916, 2020). "EfnA5 mediates Bmi1-dependent proliferation and invasion in vitro and tumour formation in an allograft model." (PMID 31988455, 2020). "In this study, a significant correlation between high expression of BMI1 and good prognostic BC features was found in the whole cohort and in the ER+ tumours." (PMID 32524353, 2020). "Collectively, our data indicated that miR-200c exerted its tumor suppressive function at least in part by restraining BMI1 expression." (PMID 33168810, 2020). "BMI1 overexpression was found as an efficient prognostic marker for NSCLC with increased tumor size, poor differentiation, more distant metastasis, and worse survival." (PMID 32726929, 2020). "The IHC staining showed a homogenous staining pattern, with BMI1 expression localised in the nuclei of the invasive tumour cells." (PMID 32524353, 2020). "BMI1 was also here demonstrated to be an independent good prognostic biomarker in ER+ tumours, independently of other clinical pathological features." (PMID 32524353, 2020). "Inhibition of BMI1 can induce apoptosis in tumor cells and elevate the sensitivity of tumor cells to chemotherapy and radiotherapy for tongue and breast cancer." (PMID 32726929, 2020). "A positive correlation between IL1R2 and BMI1 was also observed in both BC tissues and xenograft tumor tissues." (PMID 31921558, 2020). "In the MKN45, SGC-7901, MKN28, and AGS cell lines, BMI-1 upregulates the expression of miR-21, which acts as a tumor promoter and increases stem markers’ expression, tumorsphere formation, and chemoresistance." (PMID 31861404, 2019). "When mice eventually succumbed, the tumor was isolated from the brains and the amount of BMI1, EZH2, and LSD1 proteins in the treated tumors was compared against those of untreated tumors, confirming a significant increase for all three proteins." (PMID 30683859, 2019). "A similar experiment with shRNA mediated Bmi1 knockdown resulted in tumor growth inhibition in vitro and in vivo, proving that Bmi1 is a potential therapeutic target for HCC." (PMID 31466358, 2019).
tumor (continued). "Tumor growth is inhibited by FA-UA/siRNA-L in vitro and in vivo and this inhibition is contributed by a synergistic anti-tumor effect of UA and Bmi1 siRNA." (PMID 31366257, 2019). "BMI1 pharmacologic inhibition in patient-derived tumor cells decreased tumor colony formation in vitro and tumor initiation in vivo." (PMID 31366128, 2019). "Up-regulation of Bmi1 gene has been explored in several tumor types, such as nasopharyngeal carcinoma, non-small cell lung carcinoma, medulloblastoma, colon carcinoma, and metastatic melanoma." (PMID 31366257, 2019). "The results illustrated that in vitro study, there was a significant positive correlation between Bmi1 siRNA and UA co-delivered by folate-targeted liposomes to inhibit tumor cells and revealed enhanced cytotoxic effects." (PMID 31366257, 2019). "While targeting BMI-1 has been reported the effective way to decrease tumor growth, the mechanisms of inhibiting BMI-1 differ in different system with context-dependence and are somewhat unclear." (PMID 31640758, 2019). "In the current study, we continued to apply this mature folate-targeted system and for the first time examined the synergistic anti-tumor effect of Bmi1 siRNA with native compounds (UA)." (PMID 31366257, 2019). "miR‐200c inhibits the Hedgehog pathway by Bmi1, which is a known regulator of stem cell self‐renewal and tumour growth." (PMID 31599500, 2019). "In order to detect the synergistic anti-tumor effects of UA and Bmi1 siRNA delivered by FA-UA/siRNA-L, the cytotoxicity assay of various UA and Bmi1 formulations was measured in KB cells." (PMID 31366257, 2019). "We further analysed for mRNA levels of CD133, CD44, OCT4, SOX2 and BMI1, in tumour and distal margin tissues compared to the matched normal tissues expression using real‐time PCR." (PMID 30950180, 2019). "As expected the levels of expression of BMI1 increases significantly in both tumours with respect to controls (FPKM values from 18,4 to 646,6 log2FC = 5.1 in sample 554; and FPKM values from 17,8 to 50,2 log2FC = 1.4 in tumour 840)." (PMID 30914738, 2019). "BMI-1 plays a role in tumor metastasis through promoting oncogenic transformation and regulating epithelial–mesenchymal transition (EMT)." (PMID 31861404, 2019). "The Bmi1 subunit of PRC1 mediates the repression of tumor suppressors in myeloid progenitors and is required for the inhibition of tumor suppressor genes that is necessary to initiate the self-renewal of CSCs in solid tumors." (PMID 30283976, 2019). "Indirect targeting RNA can be used to regulate Bmi1 gene expression, although an effective and safe delivery system is required to transport siRNA to tumor tissue." (PMID 31366257, 2019). "Here, the authors demonstrate that BMI1 directly interacts with AR leading to increased AR signaling independently of PRC1 complex and that targeting BMI1 inhibits tumor growth of castration-resistant prostate cancer tumors." (PMID 29402932, 2018). "A recent study has confirmed overexpression of Bmi-1 protein in BC correlated with tumor classification, recurrence, TNM stage, and survival, proposing it as a possible prognostic marker." (PMID 30072631, 2018). "Most importantly, here, we show that for CRPC, especially therapy (enzalutamide)-resistant CRPC, targeting BMI1 alone or in combination with anti-AR therapy effectively kills tumor cells." (PMID 29402932, 2018). "More importantly, we demonstrate that targeting BMI1 effectively inhibits tumor growth of xenografts that have developed resistance to surgical castration and enzalutamide treatment." (PMID 29402932, 2018). "BMI-1 has been actively involved in tumor-initiating SP cells in MCL and we investigated if REC-1 SP cells are more susceptible to BMI-1 and MCL-1 reduction by PTC596 than non-SP cells." (PMID 29983879, 2018).